TMPRSS15 (transmembrane serine protease 15)
Description:
Responsible for initiating activation of pancreatic proteolytic proenzymes (trypsin, chymotrypsin and carboxypeptidase A). It catalyzes the conversion of trypsinogen to trypsin which in turn activates other proenzymes including chymotrypsinogen, procarboxypeptidases, and proelastases.
Synonyms: ENTK; PRSS7; MGC133046
Tractability: Small molecule: a structure with a bound ligand is known; a high-quality ligand is known. Antibody: UniProt predicts a signal peptide or a membrane-spanning region; the Human Protein Atlas places it where antibodies can reach. PROTAC: a small molecule that binds it is known.
Target class: Enzyme; Protease; Serine protease
Gene: Protein-coding gene on chromosome 21 (18,269,116 to 18,485,879, reverse strand). Ensembl gene ENSG00000154646.
Subcellular location: Membrane
Subcellular location (Human Protein Atlas): Plasma membrane
Gene Ontology:
Molecular function: protein binding; serine-type peptidase activity; serine-type endopeptidase activity
Biological process: protein processing; proteolysis
Cellular component: brush border; membrane
Genetic constraint (gnomAD): Loss-of-function variants: 105 observed, 110.25 expected, observed/expected ratio (o/e) 0.95, 90% interval 0.81 to 1.12. The upper end of that interval is the gene's LOEUF score, 1.12, which puts it in group 4 of 6, group 1 being the genes least tolerant of losing a copy. Missense variants: 1,123 observed, 1,119.4 expected, observed/expected ratio (o/e) 1, 90% interval 0.95 to 1.05. Synonymous variants: 391 observed, 392.74 expected, observed/expected ratio (o/e) 1, 90% interval 0.92 to 1.08.
Homologues: Orthologues: chimpanzee TMPRSS15 (99% identical), macaque TMPRSS15 (94% identical), dog TMPRSS15 (85% identical), pig TMPRSS15 (82% identical), rabbit TMPRSS15 (78% identical), mouse Tmprss15 (75% identical), rat Tmprss15 (74% identical), guinea pig TMPRSS15 (65% identical), tropical clawed frog tmprss15 (54% identical), Drosophila melanogaster Sb (13% identical), Drosophila melanogaster CG1632 (13% identical), Drosophila melanogaster CG17242 (4% identical). Paralogues in human: ST14 (21% identical), TMPRSS7 (19% identical), TMPRSS6 (17% identical), TMPRSS13 (14% identical), TMPRSS3 (14% identical), TMPRSS2 (14% identical), TMPRSS9 (13% identical), HPN (12% identical), TMPRSS5 (12% identical), TMPRSS11E (11% identical), TMPRSS11B (11% identical), TMPRSS11D (11% identical), and 5 more.
Diseases named in the same sentence as TMPRSS15 in open-access papers:
TMPRSS15 is named in the same sentence as 13 diseases in open-access papers, as found by Europe PMC text mining. Sharing a sentence is not in itself a finding about the gene and the disease. The quoted sentences say what the papers report.
enterokinase deficiency (6 papers, 2021 to 2025). "Four SNPs mapped to SYCP2L, VAV, SEPSECS, and TMPRSS15 are known to be associated with age-related hearing impairment, multiple sclerosis, pontocerebellar hypoplasia type 2, enterokinase deficiency, respectively." (PMID 38291454, 2024). "TMPRSS15 is a morbid gene, and loss-of-function variants are responsible for enterokinase deficiency." (PMID 34992628, 2021). "TMPRSS15 has been associated to enterokinase deficiency, a life-threatening intestinal malabsorption disorder characterized by diarrhea and failure to thrive." (PMID 34126920, 2021). "Additional examples include case 09DG01414 with a homozygous truncating variant in TMPRSS15 (NM_002772.2:c.2808_2809insATCA p.(Ser937Ilefs*4)) who died in infancy, an unusual presentation of enterokinase deficiency." (PMID 34645488, 2021). "PAX5 P80R subtype showed significantly expressed TMPRSS15 involved in enterokinase deficiency." (PMID 41246237, 2025). "Enterokinase deficiency (EKD,OMIM #226200) is an extremely rare autosomal recessive disease caused by mutations in the TMPRSS15 gene, which is located on chromosome 21q21.1, and contains 25 exons." (PMID 39944319, 2025). "Enterokinase deficiency (EKD, OMIM #226200) is a rare autosomal recessive genetic disease caused by mutations in the transmembrane protease serine 15 (TMPRSS15) gene." (PMID 39944319, 2025). "Enterokinase deficiency (EKD,OMIM #226200) is a rare autosomal recessive genetic disorder caused by mutations in transmembrane protease serine 15 (TMPRSS15)." (PMID 39944319, 2025).
astrocytoma (1 paper, 2016). "We first analyzed enteropeptidase gene (TMPRSS15) expression by qRT-PCR in the following cancer cell lines: MDA-MB231 (breast), MCF7 (breast), A549 (lung), U-87 MG (glioblastoma-astrocytoma), KATO-III (stomach), HT-29 (colon), and CACO-2 (colon)." (PMID 27270881, 2016).
viral infections (1 paper, 2023). "Tmprss15 collaborates in the proliferation process during viral infections, such as the influenza A virus." (PMID 37111215, 2023).
infection (2 papers, 2015 to 2021). The state of being infected such as from the introduction of a foreign agent such as serum, vaccine, antigenic substance or organism. "TMPRSS15 shares high homology in the serine protease domains of TMPRSS2, thus, may participate in the cleavage of the S protein of SARS-CoV-2 during infection." (PMID 34335974, 2021).
TMPRSS15 also shares sentences with these, for which no sentence is quoted: age-related hearing impairment (1 paper); cancer (1); Failure to thrive (1); glioblastoma (1); Hypertension (1); multiple sclerosis (1); Obesity (1); pontocerebellar hypoplasia type 2 (1); tumours (1).